PGRMC2 (progesterone receptor membrane component 2)
Diseases named in the same sentence as PGRMC2 in open-access papers (continued):
Sharing a sentence is not in itself a finding about the gene and the disease.
triple-A syndrome (1 paper, 2016). Triple A syndrome is a very rare multisystem disease characterized by adrenal insufficiency with isolated glucocorticoid deficiency, achalasia, alacrima, autonomic dysfunction and neurodegeneration. "PGRMC2 is shown to be activity regulator of CYP P450 enzymes and, therefore, to be a possible target for adrenal dysregulation in triple A syndrome." (PMID 27754849, 2016). "In summary, our work identifies microsomal PGRMC2 as novel interactor for ALADIN and provides new insights into the molecular function of the nucleoporin in the pathogenesis of triple A syndrome." (PMID 27754849, 2016).
cancer (13 papers, 2014 to 2025). A tumor composed of atypical neoplastic, often pleomorphic cells that invade other tissues. "Using a murine model, the ablation of progesterone receptor membrane component 2 (Pgrmc2) was shown to attenuate the timing, aggression, and lethality of Pten loss-of-function-induced endometrial hyperplasia and cancer." (PMID 40227710, 2025). "IL6ST, KLF4 and PGRMC2 have been linked to cancer pathogenesis, and downregulation of their mRNA expression by miR-142-3p may therefore be worth elucidating in future studies." (PMID 26657485, 2015). "This study identifies PGRMC2 as a potential therapeutic target to be inhibited in the treatment of endometrial hyperplasia and cancer, particularly where PTEN activity is reduced due to gene mutation or loss." (PMID 40227710, 2025). "In this study, we examined the effect of deleting Pgrmc2 on the development of endometrial hyperplasia and cancer using a murine phosphatase and tensin homologue (Pten) conditional loss-of-function model." (PMID 40227710, 2025). "The deletion of Pgrmc2 reduced the incidence and severity of endometrial hyperplasia and cancer in mice with conditional Pten-heterozygous uteri and increased lifespan in mice with conditional Pten-knockout uteri." (PMID 40227710, 2025). "The overexpression of PGRMC2 represses entry into the cell cycle, decreases the migration rates of cancer cells, and induces apoptosis." (PMID 39268086, 2024). "Recently, progesterone receptor membrane component (PGRMC) 1 and PGRMC2 have been shown to be highly expressed in these cancers and play important roles in promoting tumor growth and chemoresistance." (PMID 34885064, 2021). "PGRMC2, similar to PGRMC1, have been implicated in different cancer signaling cascades, yet with likely tumor suppressor properties." (PMID 34789240, 2021). "The studies presented in the following paragraphs outline a potential role for PGRMC1 and PGRMC2 in regulating both metastasis and cancer stem cell function." (PMID 34885064, 2021). "The studies indicating that PGRMC1 and potentially PGRMC2 play important roles in the growth and development of these cancers and these issues are the focus of this review." (PMID 34885064, 2021). "Pten loss-of-function-induced endometrial hyperplasia and cancer elevated uterine inflammation, but this was not impacted by PGRMC2 deficiency." (PMID 40227710, 2025). "However, to date, we are unaware of any studies that assess the function of PGRMC2 in the context of the development or progression of cancer in vivo." (PMID 40227710, 2025). "Considerably less is known about a role for PGRMC2 in cancer." (PMID 40227710, 2025). "Some proteins, such as Vimentin (VIM), Rho GDP-dissociation inhibitor 1 (Rho GDI), Lysosome-associated membrane glycoprotein 1 (LAMP1) and Membrane-associated progesterone receptor component 2 (PGRMC 2), have been previously identified as potential biomarkers for various cancers." (PMID 25477298, 2014). "The ablation of Pgrmc2 (i.e., Ptend/d; Pgrmc2d/d) did not reduce the 100% incidence of hyperplasia or cancer observed in Ptend/d mice." (PMID 40227710, 2025). "Because of the general lack of information about PGRMC2 in the context of cancer, Pgrmc2 was specifically evaluated in this context." (PMID 40227710, 2025). "In addition, among the 3686 negative aGRP DEGs, hormone receptor PGRMC2 (aGRP = − 0.635) was previously reported to be a tumor suppressor and an inhibitor of migration of cancer cell." (PMID 30390627, 2018).
tumor (7 papers, 2018 to 2025). "PGRMC1 enhances tumorigenesis in several tumor types: breast, ovary, colon, and lung cancers, whereas PGRMC2 involvement in tumorigenesis remains relatively unclear." (PMID 31036830, 2019). "The reason for this is unclear but one study offered the suggestion that PGRMC2 may function to suppress tumor metastasis of endocervical adenocarcinoma." (PMID 34885064, 2021).
infection (2 papers, 2020 to 2024). The state of being infected such as from the introduction of a foreign agent such as serum, vaccine, antigenic substance or organism. "OS at term and infection/inflammation markers can also force the downregulation of PGRMC2-mediated P4 withdrawal, creating a terminal state of EMT." (PMID 32848846, 2020).
metabolic disorders (1 paper, 2024). "When mice eat a high‐fat diet, they will have serious metabolic disorders, making mice unable to maintain their body temperature, suggesting that PGRMC2 may be a protein closely related to cell energy metabolism." (PMID 39346797, 2024).
PGRMC2 also shares sentences with these, for which no sentence is quoted: endometrioid endometrial carcinoma (1 paper); Joubert syndrome (1); Kidney Cyst (1); osteoarthritis (1).